POLE (DNA polymerase epsilon, catalytic subunit)
Diseases named in the same sentence as POLE in open-access papers (continued):
Sharing a sentence is not in itself a finding about the gene and the disease.
tumor (continued). "It is critically necessary that the clinical assay used in daily practice reliably identifies POLE mutations in the hotspot POLE-EDM as their role in tumor biology and their therapeutical consequences are known." (PMID 39239272, 2024). "Using a co-culture transwell system, we observed that EC cells with POLE P286R mutation attracted more migrated T cells in comparison to WT EC cells, suggesting an enhancement of the mutation in tumor cell migration of T cells." (PMID 38238314, 2024). "Approximately 90% of the POLE proofreading mutations are in exons 9 and 13 and are recognized as pathogenic, i.e., driver mutations that are causal for tumor genesis by ultramutation." (PMID 39239272, 2024). "Considering the close correlation between POLE mutations and increased mutation rates, it is important to define the tumor mutational burden (TMB) when describing tumor biology." (PMID 39239272, 2024). "Per available comprehensive tumor next-generation sequencing (NGS) reports, done as part of SOC practices, we’ve looked at known predictive markers of ICIs response such as tumor mutational burden and POLE/POLD mutations." (PMID 38378868, 2024). "Group 3 tumors with V411 L driver that had the highest mTMBs tended to have multiple POLE variants (2 to 8) per tumor, with a range of structure stabilizing or destabilizing variants." (PMID 38282550, 2024). "Our findings provide valuable insights into the anti-tumor effects of POLE mutations and offer potential strategies for the effective treatment of human ECs." (PMID 38238314, 2024). "Based on the TCGA database, we investigated the tumor microenvironment (TME) of POLE mutations, focusing on immune cells and co-expression genes." (PMID 38023184, 2023). "The second variant of uncertain significance in POLE detected on the same germline test for this patient was also missing from the tumor CGP results." (PMID 35962742, 2023). "The excellent prognosis of the group of POLE-mutated tumors has been validated in numerous series of cases, and has led to incorporation of POLE mutation testing in tumor stratification in international guidelines, such as by ESGO-ESTRO-ESP and FIGO." (PMID 37874375, 2023). "POLE-mutant tumors gained a massive amount of mutations conferring an extremely high median tumor mutational burden (TMB) (325.40 mutations/Mb)." (PMID 36675305, 2023). "C8 is also a homogeneous iCluster, dominated by a single tumor type, with the POLE mutation present in highly somatically mutated cells." (PMID 37085609, 2023). "Most tumors classified as MMRd by IHC, the POLE-mutated tumor, and all cases with PDL1 expression belonged to this cluster." (PMID 37353806, 2023). "Some studies found higher stromal TILs than intraepithelial, and one study found higher TILs in MMRdef tumors compared to POLE, which can be explained by the similarities of ultra- and hyper-mutated cancers with possibly similar tumor mutational burden." (PMID 37035329, 2023). "The NCCN Clinical Practice Guidelines: Uterine Neoplasms (version 1, 2023) and related studies have proven that POLE-mutated ECs harbored a high tumor mutational burden (TMB), infrequent recurrence, and a favorable prognosis." (PMID 38023184, 2023).
tumor (continued). "It detected a tumor mutational burden of >150 mutations per megabase along with a pathogenic mutation in POLE P436R with a variant allele frequency of 33%." (PMID 37239414, 2023). "To our knowledge, we are the first to study tumor mutation burden of germline variant POLE c.1373A > T p.(Tyr458Phe) and the first to use human isogenic cell lines to study the function of germline POLE variants." (PMID 36856825, 2023). "We describe its molecular characteristics, including the mutant sites in PolE, the mutation signature of this type of tumor, and the progress in the molecular mechanism of its ultramutagenesis and carcinogenicity." (PMID 35326618, 2022). "Inactivating mutations in the exonuclease domain of POLE induce somatic hypermutation resulting in a high tumor mutation burden (TMB) and are associated with immune checkpoint inhibitor (ICI) benefit." (PMID 35274726, 2022). "POLE/POLD1 mutation is not only closely related to tumor formation, but also a potential molecular marker for predicting the efficacy of immunotherapy in pan-cancer species." (PMID 35780178, 2022). "Pathogenic somatic mutations in the proofreading domain of POLE have been found in some tumor types, such as endometrial tumors (8%) and at lower frequencies in colorectal, glioblastoma, ovary, prostate, breast, or gastric cancer." (PMID 35463299, 2022). "This discordance is intriguing, as ultramutated (typically >100 mutations/Mb) tumours with POLE exonuclease domain mutations display excellent prognosis in both tumour types." (PMID 35262923, 2022). "Among the 20 cases in the POLE-ultramutated subgroup, the most common hotspot mutations (P286R and V411L) were found in 10 (50%) and seven (35%) tumor samples, respectively." (PMID 36003784, 2022). "Presence of POLE mutations and signature 10 in a hypermutated tumor suggested that these POLE mutations were pathogenic." (PMID 34351088, 2022). "Other studies showed that the expression of immune checkpoint related proteins such as PD-1 and cytotoxic T lymphocyte associated antigen-4 (CTLA-4) is increased in POLE-mutated EC, and the number of tumor-infiltrating T cells is high." (PMID 35780178, 2022). "One patient carried an inactivating POLE mutation leading to a clearly hypermutated progressed tumor." (PMID 35982066, 2022). "The tumor mutation burden (TMB) levels of POLE mutant and MSI-H cases were significantly higher than that of the other two subtypes (p< 0.001)." (PMID 36532042, 2022). "One possible underlying mechanism is that POLE mutations lead to tumor hypermutation and increase the expression of tumor neoantigens." (PMID 35780178, 2022). "Mutation signature analyses revealed that, in microsatellite-stable (MSS) tumors, DNA repair mutations were common for both tumor initiation and progression, while tobacco, POLE, and inflammation signatures likely initiate carcinogenesis." (PMID 36970058, 2022). "POLE ultra-mutated tumours exhibit few copy number aberrations and have mutations in PTEN, PIK3RI, PIK3CA, FBXW7 and KRAS genes." (PMID 35530346, 2022). "Despite being able to mount an anti-tumor immune response, some patients with PolE mutation present with bulky tumors." (PMID 35326618, 2022). "On the contrary, the literature data suggest that high tumor mutational burden is characteristic for tumors with defects in POLE/POLD1 genes." (PMID 35562977, 2022). "ctDNA from the plasma and peritoneal fluid of EC4 and plasma ctDNA from EC5 with POLE mutations showed a high tumor mutational burden (TMB) of ≥20 mutations per megabase." (PMID 35626111, 2022). "Pembrolizumab is also approved for those patients whose tumors demonstrate a high tumor mutational burden, such as those with POLE mutations." (PMID 36139624, 2022).
tumor (continued). "Some scholars have suggested that tumors with a mutation in the POLE gene can exhibit the differential regulation of tumor cell metabolism through glucose metabolism." (PMID 35800058, 2022). "TCGA showed that ECs with POLE mutations exhibited a high mutational burden in tumor gDNA, and a consensus in ctDNA was further identified by investigating all samples with POLE mutations." (PMID 35626111, 2022). "POLE/POLD1 mutations are not only closely related to tumor formation, but are also a potential molecular marker for predicting the efficacy of immunotherapy in pan-carcinomatous species." (PMID 35780178, 2022). "The MAF of the POLE mutation was ~49%, indicating that the mutation is a somatic heterozygous variant present in almost all tumor cells." (PMID 34351088, 2022). "Increased neoantigen loads and high density of TILs were also observed in patients with POLE mutation across multiple tumor types, suggesting better response to immunotherapy 66,67." (PMID 35069896, 2022). "Given the known association of POLE exonuclease domain mutations with increased tumour T‐cell infiltrate, we excluded these from our analysis." (PMID 35262923, 2022). "In contrast, heterozygous exonuclease mutations in POLD1 and POLE are readily detected by sequencing tumor or germline DNA." (PMID 36291559, 2022). "POLE-mutated tumor have been reported to have a high numbers of tumor-infiltrating lymphocytes and high neo-antigen loads, which suggest they would respond well to immunotherapy." (PMID 35834061, 2022). "Specific mutational signatures have been identified in tumours with mutations in the exonuclease (proofreading) domain of polymerase epsilon (POLE), as well as tumours with mutations or epigenetic silencing of MMR genes." (PMID 36010882, 2022). "In 2013, a molecular diagnostic classification published by The Cancer Genome Atlas (TCGA) Research Network defined four prognostic categories: POLE ultra-mutated, microsatellite instability hypermutated, low copy-number tumor, and high copy-number tumor." (PMID 35269674, 2022). "The DNA polymerase epsilon catalytic subunit A (POLE) participates in DNA replication and DNA repair pathways, playing a crucial role in tumor mutations." (PMID 35069896, 2022). "When examining tumor samples, one sample showed a stop-gain mutation in PolE as well as mutations in DNA-dependent protein kinase catalytic subunit (PRKDC or DNA-PK)." (PMID 35326618, 2022). "Multivariate Cox regression analysis after adjustment for MSI status and tumor type showed that POLE/POLD1 is an independent risk factor for immunotherapy benefit." (PMID 35780178, 2022). "By contrast, N2 contains non-infiltrating cells that express CD8, PD1 and FoxP3 (P2) associated to tumor CK+ cells (P7), and is associated with POLE mutated patients." (PMID 35217454, 2022). "The first group, known as POLE ultramutated, includes tumours with inactivating mutations in POLE exonuclease." (PMID 35326558, 2022). "POLE‐mutated CRCs arose in the transverse colon and rectum, and showed increased tumor‐infiltrating lymphocytes and immune cells at the tumor–stromal interface." (PMID 35795065, 2022). "In contrast to mismatch repair-deficient hypermutated (>10 mutations/Mb) cancer, PolE-associated cancer is primarily microsatellite stable (MSS) In this article, we provide a comprehensive review of this PolE-associated ultramutated tumor." (PMID 35326618, 2022).
tumor (continued). "Only one MMRp tumor carried a pathogenic mutation (P286C) involving the exonuclease domain of POLE (T33)." (PMID 33435234, 2021). "Nearly all of the patients (30 of 31) with stage III and IV SWI/SNF‐deficient tumors died from their disease, except for one patient with stage IV ARID1A/1B‐deficient tumor that also harbored a POLE V411L mutation." (PMID 33125840, 2021). "None of the patients with synchronous multiple cancers displayed POLE mutations in their cancer tissues; thus, patients with synchronous multiple cancers were analysed by the most advanced tumour lesion for further molecular studies." (PMID 34034807, 2021). "Although we analysed over 1,000 CRC samples, CRCs with POLE proofreading mutations were found in only four tumours." (PMID 34034807, 2021). "POLE mutations are associated with high tumor mutational burden and are considered as an emerging biomarker for immunotherapy in some tumor models." (PMID 33722295, 2021). "The tumor mutational burden (TMB) attributed to COSMIC signature 10 of our POLE cases spans from over five to more than 75 mutations per megabase." (PMID 34158040, 2021). "The authors reported four prognostic categories, as follows: POLE ultra-mutated, microsatellite instability hypermutated, low copy-number tumor, and high copy-number tumor." (PMID 34830129, 2021). "Somatic POLE exonuclease domain mutations occur early, quite possibly initiating events in sporadic cancers, and forcefully shape subsequent tumor evolution." (PMID 34150634, 2021). "Somatic POLE mutations in CRCs are associated with enhanced tumour immunogenicity and increased CD8-positive lymphocytic infiltration." (PMID 34034807, 2021). "POLE‐mutated tumors have an extremely high tumor mutation burden (TMB), and the disruption by pathogenic heterozygous mutations found in cancers leads to a phenotype of tumor ultramutation, which produces an increase in neoantigens." (PMID 33125191, 2021). "POLE mutations accompanied by an ultra-tumor mutation burden presented with a favorable clinical outcome." (PMID 34439385, 2021). "Fourth, functional enrichment analysis and the role of POLE in the immune-cell infiltration of the tumor microenvironment were closely linked to cancer treatment and the development of targeted drugs." (PMID 34950188, 2021). "In conclusion, the present study is the first to our knowledge to indicate that elevated POLE expression is significantly associated with poor survival and an immune-suppressive tumor microenvironment in ccRCC." (PMID 34950188, 2021). "PPAP is caused by germline pathogenic variants in the exonuclease domains of POLD1 or POLE genes, and affected families have an increased risk for a number of tumours also prevalent in LS, in particular CRC and EC." (PMID 33499123, 2021). "The present study provides compelling data supporting the conclusion that elevated POLE expression is significantly linked with poor outcomes and the immune-suppressive tumor microenvironment of ccRCC." (PMID 34950188, 2021). "Pathogenic mutation of DNA polymerase epsilon catalytic subunit (POLE) is associated with high tumor mutation burden (TMB) and response to immune checkpoint inhibitor (ICI) in several cancers." (PMID 34345822, 2021). "Three EC cases were classified as POLE mutation (POLEmut)-type, which had a very high tumor mutation burden (TMB) and low microsatellite instability (MSI)." (PMID 35002543, 2021). "The most striking molecular characteristic in tumours harbouring many somatic POLE EDMs is their very high mutation rate, often exceeding 100 mutations/Mb." (PMID 34228709, 2021). "We subsequently used hierarchical cluster analysis to identify the DEGs associated with POLE in ccRCC and analyzed in detail their differences between tumor and normal tissue." (PMID 34950188, 2021).
tumor (continued). "To better understand the differences between tumours with POLE mutations and the other subtypes, we evaluated the methylation status of discrete regions within the promoter of the MGMT and SFRP2 genes." (PMID 34034807, 2021). "POLE-driven tumors are associated with a distinct mutational signature found in whole-genome sequencing from tumor-normal pairs which is characterized by a high number of TCT > TAT and TCG > TTG mutations." (PMID 34158040, 2021). "Increasing evidence indicates that DNA polymerase epsilon (POLE), which mediates DNA damage repair, is significantly associated with tumor prognosis." (PMID 34950188, 2021). "Our results are further supported in the literature, where some MSS tumours shown to harbour DNA polymerase ε (POLE) mutations and a hypermutated phenotype were shown to be enriched in neoantigens and tumour-infiltrating immune cells." (PMID 33228141, 2020). "A scoring system to assess these alterations (POLE‐score) was developed; based on their scores, 7/18 (39%) additional tumours with EDM were classified as POLE‐ultramutated ECs, and the six POLE mutations present in these tumours were considered pathogenic." (PMID 31829442, 2020). "Forty‐eight out of 54 (88.9%) ECs scoring ≥ 3 points had a recurrent POLE mutation (including hotspot mutations), compared with 7/28 (25%) tumours scoring ≤ 2 points (p ≤ 0.001, χ2 statistics)." (PMID 31829442, 2020). "Low POLE expression plays a pivotal role in accumulation of mutations and onset of cancer, contributing to development and growth of tumor cells." (PMID 32433714, 2020). "Targeted sequencing can predict the presence of POLE mutations based on the tumor mutational burden." (PMID 33256706, 2020). "This included 82 tumours with a somatic POLE mutation, of which 59 (72%) were located within the exonuclease domain and 23 (28%) outside the exonuclease domain." (PMID 31829442, 2020). "We identified six samples with high tumor mutational burden and POLE mutation consistent with TCGA group 1." (PMID 33256706, 2020). "We carried out the analysis of this sample by using a gene-targeted NGS panel validated in our laboratory for testing POLE mutations and identified the hotspot POLE p.P286R mutation in this tumor at 44% of allelic frequency." (PMID 32642724, 2020). "We defined tumours with POLE hotspot mutations as a set of ‘true positives’, for subsequent identification of genomic alterations associated with pathogenic POLE mutations." (PMID 31829442, 2020). "Mutations in the proofreading domain of POLE have been reported as pathogenic, resulting in approximately a 100-fold increase of the mutation rate, thereby increasing the tumor mutational burden (TMB)." (PMID 32365882, 2020). "Tumours with any of the 11 POLE EDMs identified in the TCGA and classified as pathogenic by POLE‐score should be classified as ‘POLE ultramutated’ EC, independently of MMRd/MSI status." (PMID 31829442, 2020). "The co‐existence of POLE mutations and MMRd/MSI in EC 26, 38 and the variation in its prevalence by POLE mutation location raise important questions about which is the initial, presumably dominant factor determining tumour phenotype and clinical outcome." (PMID 31829442, 2020). "Mutant and high expression of POLE correlated with favorable prognosis with increased TILs and tumor mutation burden, compared with wild type and low expression of POLE." (PMID 32433714, 2020). "As expected, the germlineframeshift mutation in POLE was also detected in tumor sequencing, witha VAF = 0.51 (total coverage = 242 reads), supporting its germline origin." (PMID 33001133, 2020). "For the tumor suppressors, there are 3 up-regulated genes (mutations: POLE; CNAs: DNMT3B, RECQL4) and 2 down-regulated genes (CNAs: SDHA; fusions: ZFHX3)." (PMID 32934781, 2020). "We consider tumor sequence analysis of utmost importance for a proper classification of POLE and POLD1 ED variants." (PMID 32792570, 2020).